ENSG00000197991 (novel protein)
Gene: Protein-coding gene on chromosome 13 (61,409,858 to 61,427,849, reverse strand). Ensembl gene ENSG00000197991.
Genetic constraint (gnomAD): Loss-of-function variants: 18 observed, 38.48 expected, observed/expected ratio (o/e) 0.47, 90% interval 0.32 to 0.69. Missense variants: 1,161 observed, 1,217.4 expected, observed/expected ratio (o/e) 0.95, 90% interval 0.91 to 1. Synonymous variants: 495 observed, 473.59 expected, observed/expected ratio (o/e) 1.05, 90% interval 0.97 to 1.13.